YRDC (yrdC N6-threonylcarbamoyltransferase domain containing)
Description:
Cytoplasmic and mitochondrial threonylcarbamoyl-AMP synthase required for the formation of a threonylcarbamoyl group on adenosine at position 37 (t(6)A37) in tRNAs that read codons beginning with adenine. Catalyzes the conversion of L-threonine, HCO(3)(-)/CO(2) and ATP to give threonylcarbamoyl-AMP (TC-AMP) as the acyladenylate intermediate, with the release of diphosphate. Participates in t(6)A37 formation in cytoplasmic and mitochondrial tRNAs. May regulate the activity of some transporters (By similarity).
Synonyms: DRIP3; IRIP; FLJ23476; SUA5; GAMOS10
Tractability: Antibody: UniProt places it where antibodies can reach, with medium confidence; its Gene Ontology location is reachable by antibodies, with medium confidence. PROTAC: ubiquitination databases record sites on it; its protein half-life has been measured.
Gene: Protein-coding gene on chromosome 1 (37,802,945 to 37,808,208, reverse strand). Ensembl gene ENSG00000196449.
Subcellular location: Cytoplasm; Mitochondrion; Cell membrane
Subcellular location (Human Protein Atlas): Mitochondria
Pathways (Reactome):
Metabolism of RNA: tRNA modification in the mitochondrion
Gene Ontology:
Molecular function: L-threonylcarbamoyladenylate synthase; protein binding; nucleotidyltransferase activity; tRNA binding; double-stranded RNA binding
Biological process: negative regulation of transport; tRNA threonylcarbamoyladenosine modification; mitochondrial tRNA modification; regulation of translational fidelity
Cellular component: cytoplasm; mitochondrion; mitochondrial matrix; plasma membrane; membrane
Genetic constraint (gnomAD): Loss-of-function variants: 19 observed, 22.15 expected, observed/expected ratio (o/e) 0.86, 90% interval 0.6 to 1.26. The synonymous counts are far from expectation, so gnomAD's model fits this gene poorly and the ratio says little. Missense variants: 380 observed, 320.27 expected, observed/expected ratio (o/e) 1.19, 90% interval 1.09 to 1.29. Synonymous variants: 193 observed, 141.72 expected, observed/expected ratio (o/e) 1.36, 90% interval 1.21 to 1.53.
Homologues: Orthologues: chimpanzee YRDC (99% identical), macaque YRDC (99% identical), rabbit YRDC (92% identical), pig YRDC (91% identical), guinea pig YRDC (87% identical), dog YRDC (86% identical), mouse Yrdc (86% identical), rat Yrdc (73% identical), tropical clawed frog yrdc (54% identical), zebrafish yrdc (48% identical), Drosophila melanogaster Tcs1 (39% identical), Caenorhabditis elegans Y48C3A.18 (32% identical).
Diseases named in the same sentence as YRDC in open-access papers:
YRDC is named in the same sentence as 44 diseases in open-access papers, as found by Europe PMC text mining. Sharing a sentence is not in itself a finding about the gene and the disease. The quoted sentences say what the papers report.
bladder cancer (3 papers, 2017 to 2025). "Previous studies have shown that MicroRNA‐206 regulated bladder cancer development via targeting YRDC." (PMID 40898423, 2025). "Recent studies have indicated that YRDC functions as an oncogene and can promote cell proliferation in bladder cancer." (PMID 36897170, 2023). "MicroR-206 also acts as a tumor suppressor in bladder cancer and colorectal cancer via targeting YRDC and FMNL2, which are closely related to the tumor cell proliferation and EMT." (PMID 28615991, 2017).
hepatocellular carcinoma (3 papers, 2021 to 2025). A malignant tumor that arises from hepatocytes. "In the current study, we firstly found that the YRDC expression was associated with the sensitivity of lenvatinib in hepatocellular carcinoma cells." (PMID 34658879, 2021). "A recent study reported that activation of the MEK/ERK pathway by YRDC promoted the proliferation of hepatocellular carcinoma." (PMID 40898423, 2025). "The promotion of hepatocellular carcinoma cell proliferation was thought to be a result of YRDC's positive effect on MEK/ERK signaling pathways." (PMID 40898423, 2025). "As the same as the previous study has shown, YRDC was highly expressed in lung cancer and hepatocellular carcinoma, and the knockdown and overexpression model validated the expression and protein level of YRDC in cell lines." (PMID 40898423, 2025). "Our previous study found that the expression of YRDC was dysregulated in the hepatocellular carcinoma tissues." (PMID 34658879, 2021). "Our previous study reported that the expression of YRDC was dysregulated in hepatocellular carcinoma tissues." (PMID 34658879, 2021).
congenital hypothyroidism (2 papers, 2019 to 2021). A thyroid hormone deficiency present from birth. "Considering the phenotypic overlap of all four patients, we postulate that patients with homozygous or compound heterozygous YRDC mutations should be viewed as a distinct entity based on the specific phenotypic features of congenital hypothyroidism, progeroid appearance and premature death." (PMID 34545459, 2021). "In addition, we have expanded the GAMOS phenotype spectrum by describing congenital hypothyroidism to be associated with YRDC mutations." (PMID 31481669, 2019).
sarcoma (2 papers, 2023 to 2025). A usually aggressive malignant neoplasm of the soft tissue or bone. "Kaplan-Meier survival curves from the TCGA sarcoma dataset demonstrated that increased expression patients (cut-off by the median gene expression value) of EIF4B or YRDC had a lower 10-year overall survival rate." (PMID 36897170, 2023).
breast invasive carcinoma (1 paper, 2025). "For instance, elevated levels of YRDC might indicate aggressive tumor behavior in breast invasive carcinoma, cholangiocarcinoma, head and neck squamous cell carcinoma, liver hepatocellular carcinoma, and lung adenocarcinoma." (PMID 40898423, 2025).
developmental delay (1 paper, 2019). "In addition to developmental delay, primary microcephaly was present in the two affected children of one family with YRDC mutations, whereas the affected child in the second YRDC family and all GON7-mutated individuals presented with post-natal microcephaly." (PMID 31481669, 2019).
Galloway-Mowat syndrome (1 paper, 2019). Galloway syndrome is characterized by the association of nephrotic syndrome and central nervous system anomalies. "Here, the authors report mutations in YRDC and the KEOPS component GON7 in Galloway-Mowat syndrome and determine the crystal structure of a GON7-containg subcomplex that suggests a role in KEOPS complex stability." (PMID 31481669, 2019).
glioblastoma (1 paper, 2025). The most malignant astrocytic tumor (WHO grade IV). "In glioblastoma (GBM), threonine drives tumor growth by fueling codon-biased protein synthesis through transfer RNA (tRNA) modifications mediated by the enzyme YRDC." (PMID 41347155, 2025).
MERRF (1 paper, 2022). A mitochondrial encephalomyopathy characterized clinically by a mixed seizure disorder, myoclonus, progressive ataxia, spasticity, and a mild myopathy. "Deletion of YRDC and OSGEPL1 causes mitochondrial dysfunction (interferes with protein synthesis and respiratory activities) and is clinically associated with an onset of myoclonus epilepsy with ragged-red fibers (MERRF)." (PMID 36362385, 2022).
ovarian serous cystadenocarcinoma (1 paper, 2025). A malignant serous cystic epithelial neoplasm arising from the ovary. "Secondly, using the TISCH database, the cellular expression level of YRDC was relatively higher in tumor cells than in other cell types (e.g., immune cells, stromal cells, etc.)in uveal melanoma (UVM), STAD, skin cutaneous melanoma (SKCM), ovarian serous cystadenocarcinoma (OV), HNSC, and BRCA." (PMID 40898423, 2025).
thymoma (1 paper, 2025). A neoplasm arising from the epithelial cells of the thymus. "Otherwise, a better prognosis was observed in patients with high YRDC expression compared to patients with low YRDC expression in only four tumors, including thymoma (THYM), STAD, COAD, and kidney renal clear cell carcinoma (KIRC) (p < 0.05, univariate Cox regression)." (PMID 40898423, 2025).
Thyroid carcinoma (1 paper, 2025). "There were four of 23 tumor tissues with decreased YRDC RNA levels (p < 0.05, Wilcoxon test), including Kidney Chromophobe (KICH), Kidney renal clear cell carcinoma (KIRC), Kidney renal papillary cell carcinoma (KIRP), and Thyroid carcinoma (THCA)." (PMID 40898423, 2025).
tumor (6 papers, 2017 to 2025). "High levels of YRDC caused tumor progression by accelerating cell proliferation and drug resistance." (PMID 40898423, 2025). "Our results also implicated that tumor cells might acquire drug resistance due to the high level of YRDC." (PMID 40898423, 2025). "Our previous results showed that YRDC was associated with the unfolded protein response, suggesting that YRDC may be associated with tumor drug resistance." (PMID 40898423, 2025). "In BLCA, READ, and SARC, higher expression of YRDC was observed in tumor tissues than in normal tissues." (PMID 40898423, 2025). "In summary, YRDC was suggested as a potential innovative biomarker for tumor patients prognosis, immunotherapy response, and targeted drug's efficacy." (PMID 40898423, 2025). "We presented a bioinformatics analysis of the possible pro‐tumor molecular mechanisms and biomarker role of YRDC." (PMID 40898423, 2025). "The results indicated that YRDC knockdown or lenvatinib treatment significantly inhibited the tumor growth, exhibited as declined tumor volume, and decreased tumor weight." (PMID 34658879, 2021). "It is suggested that the expression level of YRDC may be involved in immune cell infiltration in the tumor microenvironment." (PMID 40898423, 2025). "Our results showed that YRDC RNA expression was significantly correlated with CNV in a variety of tumors (Pearson correlation coefficient > 0.2 and p < 0.05), suggesting that the increased CNV may be responsible for the high YRDC expression in tumor tissues." (PMID 40898423, 2025). "Then, publicly available CRISPR Screening data was used to determine whether YRDC can promote tumor cell proliferation." (PMID 40898423, 2025). "Moreover, while threonine availability has been mechanistically linked to YRDC-dependent translation and tumor growth, this evidence comes from GBM models and tumor subtypes." (PMID 41347155, 2025). "Although this modification has been observed in a subset of GBM models, potential biomarkers may include YRDC enzymatic activity, high t6A modification levels in tumor RNA, or metabolic features of threonine accumulation." (PMID 41347155, 2025). "Therefore, we compared the methylation levels of YRDC genes in tumor tissues and normal tissues by using Oncodb." (PMID 40898423, 2025). "In other words, YRDC was highly expressed in various tumor tissues." (PMID 40898423, 2025). "On the basis of multi‐omics data, we found that the high expression of YRDC in tumor tissues may be the result of YRDC CNV and aberrant methylation, which explains part of the phenomenon of highly expressed YRDC in cancer." (PMID 40898423, 2025). "Given the known relevance of these pathways to tumor progression, we speculate that YRDC likely influences tumor proliferation and drug resistance through those pathways." (PMID 40898423, 2025). "Furthermore, another study has demonstrated that miR-206 targets YRDC to suppress tumor development in BC." (PMID 39777350, 2024). "In addition, the wound healing and transwell assays revealed the inhibition of eIF4B and YRDC reduced tumor cells migration and invasion." (PMID 36897170, 2023). "Additionally, YRDC might promote cancer via enhancing tumor cell proliferation, modulating immune cell infiltration, and enhancing drug resistance." (PMID 40898423, 2025). "Moreover, almost all available data have shown that YRDC was mainly expressed in tumor cells." (PMID 40898423, 2025). "However, the knockdown of YRDC could weaken the lenvatinib-mediated tumor growth inhibition, mainly reflecting in the inhibition of tumor weight (66 vs. 91%)." (PMID 34658879, 2021). "These information suggested that HCC cells or tumor with high expression of YRDC, containing higher basal activity of the MEK/ERK, might be more sensitive, or responsive, to lenvatinib, and that those with low expression of YRDC might be resistant to lenvatinib." (PMID 34658879, 2021).
tumor (continued). "We observed that YRDC expression levels were inversely correlated with CD8+ T cells, memory B cells, plasma cells, and activated NK cells in most of the tumor tissues." (PMID 40898423, 2025). "We constructed YRDC co‐expression gene networks in each tumor data, and based on which, a GSEA analysis was further performed to explore the function of YRDC." (PMID 40898423, 2025). "CircRBMS3 knockdown in tumor tissues resulted in a significant overexpression of terminal dUTP nick end labeling (TUNEL)-positive cells, whereas the levels of Ki67, eIF4B or YRDC were decreased, while inhibition of miR-424 reversed these effects." (PMID 36897170, 2023). "EIF4B and YRDC are known as oncogenes in some tumor types, while their function in OS is currently not understood." (PMID 36897170, 2023). "Meanwhile, YRDC overexpression cells showed more sensitivity to lenvatinib compared with its control cells when evaluated by tumor weight (78 vs. 67%), however, not significantly different when evaluated by tumor volume." (PMID 34658879, 2021). "The low YRDC expression could significantly inhibit the activity of MEK/ERK and inhibit the proliferation of HCC cells in vitro as well as the tumor growth in vivo." (PMID 34658879, 2021).
cancer (2 papers, 2019 to 2025). A tumor composed of atypical neoplastic, often pleomorphic cells that invade other tissues. "In the gene co‐expression network, we observed that YRDC was associated with the expression of multiple immune cell signature genes at the pan‐cancer level, including T‐cell signature genes (CD3D, CD4, CD8A, CD8B), B‐cell signature genes (CD19, MS4A1), and multiple immunoglobulin genes." (PMID 40898423, 2025). "The comprehensive pan‐cancer analysis provides a broad perspective on YRDC's role across multiple cancer types." (PMID 40898423, 2025). "This study aimed to comprehensively investigate YRDC's role in pan‐cancer and to explore the potential effects of YRDC on the immune infiltration pattern and anticancer drug sensitivity." (PMID 40898423, 2025). "This study will help us more clearly understand the role of YRDC in cancer and lay some groundwork for future research to validate and elucidate the mechanisms of YRDC in tumorigenesis and anticancer drug efficacy." (PMID 40898423, 2025). "YRDC can promote the proliferation of cancer cells, and it was considered to be a proliferation‐associated protein." (PMID 40898423, 2025). "Our study identifies YRDC as a novel therapeutic target and a promising biomarker for cancer progression, immunotherapy response, and targeted drug sensitivity across pan‐cancers." (PMID 40898423, 2025). "YRDC has emerged as a potential biomarker in cancer, yet its prognostic value, oncogenic mechanisms, role in immune infiltration, and anticancer drugs efficacy in pan‐cancer remained poorly understood." (PMID 40898423, 2025). "These firstly provide evidence for YRDC as a prognostic and drug sensitivity marker in pan‐cancer." (PMID 40898423, 2025). "Thus, we performed a comprehensive bioinformatics analysis with multi‐omics data to show the expressions and prognostic values of YRDC in pan‐cancer." (PMID 40898423, 2025). "Additionally, it provided a comprehensive analysis of YRDC's molecular mechanisms at a pan‐cancer level, which can help to further investigate its potential mechanisms in tumorigenesis and malignant progression." (PMID 40898423, 2025). "YRDC was believed to play a critical role in the occurring development of cancers." (PMID 40898423, 2025). "However, whether YRDC expression was a common mechanism of tumorigenesis and progression at the pan‐cancer level was still unclear." (PMID 40898423, 2025). "In the end, CCT6A, UTP18, YRDC, RRP12, RFT1, NLE1, and DDOST were essential genes across pan-cancer including COAD cells." (PMID 31867042, 2019). "In addition, CCT6A, UTP18, YRDC, RRP12, RFT1, NLE1, as well as DDOST were essential genes across pan-cancer including COAD cells, and ACTG1 and RHOQ were less essential genes in cancer cells." (PMID 31867042, 2019). "Dependency score analysis by DepMap showed that ACTG1 and RHOQ were less essential across pan-cancer cells including COAD cell lines, and CCT6A, UTP18, YRDC, RRP12, RFT1, NLE1, as well as DDOST were essential across pan-cancer cells including most of COAD cell lines." (PMID 31867042, 2019).
neurological diseases (1 paper, 2022). "Pathogenic mutations of YRDC, OSGEPL1 and KEOPS are implicated in a number of human mitochondrial and neurological diseases, including autosomal recessive Galloway–Mowat syndrome." (PMID 36362385, 2022).
YRDC also shares sentences with these, for which no sentence is quoted: glioma (2 papers); osteosarcoma (2); adrenocortical carcinoma (1); brain disorder (1); cervical squamous cell carcinoma (1); cholangiocarcinoma (1); cholestasis (1); colon cancer (1); colorectal cancer (1); endocervical adenocarcinoma (1); esophageal carcinoma (1); fungal meningitis (1); head and neck squamous cell carcinoma (1); kidney chromophobe (1); kidney disease (1); lung adenocarcinoma (1); lung carcinoma (1); lung squamous cell carcinoma (1); mesothelioma (1); microcephaly (1); myoclonus epilepsy (1); ovarian carcinoma (1); phospholipidosis (1); Primary microcephaly (1); prostate adenocarcinoma (1); skin cutaneous melanoma (1); uterine carcinosarcoma (1); uterine corpus endometrial carcinoma (1); uveal melanoma (1).